B3GNT5 (UDP-GlcNAc:betaGal beta-1,3-N-acetylglucosaminyltransferase 5)
Description:
Beta-1,3-N-acetylglucosaminyltransferase that plays a key role in the synthesis of lacto- or neolacto-series carbohydrate chains on glycolipids, notably by participating in biosynthesis of HNK-1 and Lewis X carbohydrate structures. Has strong activity toward lactosylceramide (LacCer) and neolactotetraosylceramide (nLc(4)Cer; paragloboside), resulting in the synthesis of Lc(3)Cer and neolactopentaosylceramide (nLc(5)Cer), respectively. Probably plays a central role in regulating neolacto-series glycolipid synthesis during embryonic development.
Synonyms: Beta3Gn-T5; B3GN-T5
Tractability: Antibody: UniProt predicts a signal peptide or a membrane-spanning region.
Gene: Protein-coding gene on chromosome 3 (183,249,324 to 183,298,504, forward strand). Ensembl gene ENSG00000176597.
Subcellular location: Golgi apparatus membrane
Subcellular location (Human Protein Atlas): Nucleoli
Pathways (Reactome):
Metabolism: Glycosphingolipid biosynthesis
Metabolism of proteins: O-linked glycosylation of mucins
Gene Ontology:
Molecular function: lactosylceramide 1,3-N-acetyl-beta-D-glucosaminyltransferase activity; protein binding; hexosyltransferase activity
Biological process: central nervous system development; glycolipid biosynthetic process; glycoprotein biosynthetic process; glycosphingolipid biosynthetic process; carbohydrate derivative metabolic process; sphingolipid biosynthetic process
Cellular component: Golgi membrane; membrane
Genetic constraint (gnomAD): Loss-of-function variants: 11 observed, 32.06 expected, observed/expected ratio (o/e) 0.34, 90% interval 0.22 to 0.57. The upper end of that interval is the gene's LOEUF score, 0.57, which puts it in group 2 of 6, group 1 being the genes least tolerant of losing a copy. Missense variants: 385 observed, 483.19 expected, observed/expected ratio (o/e) 0.8, 90% interval 0.73 to 0.87. Synonymous variants: 166 observed, 167.6 expected, observed/expected ratio (o/e) 0.99, 90% interval 0.87 to 1.13.
Homologues: Orthologues: chimpanzee B3GNT5 (100% identical), macaque B3GNT5 (96% identical), rabbit B3GNT5 (88% identical), pig B3GNT5 (86% identical), guinea pig B3GNT5 (85% identical), rat B3gnt5 (80% identical), mouse B3gnt5 (79% identical), tropical clawed frog b3gnt5 (62% identical), zebrafish b3gnt5a (56% identical), zebrafish b3gnt5b (52% identical), Drosophila melanogaster brn (21% identical), Caenorhabditis elegans bre-5 (17% identical), and 2 more. Paralogues in human: B3GNT7 (28% identical), B3GALT9 (28% identical), B3GNT4 (27% identical), B3GNT2 (26% identical), B3GNT3 (26% identical), B3GNT6 (26% identical), B3GALT2 (26% identical), B3GNT9 (25% identical), B3GALT1 (25% identical), B3GALT5 (24% identical), B3GALT4 (24% identical), B3GNT8 (24% identical), and 3 more.
Diseases named in the same sentence as B3GNT5 in open-access papers:
B3GNT5 is named in the same sentence as 29 diseases in open-access papers, as found by Europe PMC text mining. Sharing a sentence is not in itself a finding about the gene and the disease. The quoted sentences say what the papers report.
glioblastoma (8 papers, 2010 to 2024). The most malignant astrocytic tumor (WHO grade IV). "In addition, the enzyme of the B3GNT5 gene product, which converts lacCer to lactotriaosylceramide, has been found to be significantly elevated in the tumors of patients with glioblastoma multiforme and was associated with decreased overall survival." (PMID 37190166, 2023). "For instance, research suggests that the suppression of the expression of β3GNT5 can reduce the formation of neurospheres, and glioblastoma patients with high β3GNT5 expression show explicitly reduced OS." (PMID 37771444, 2023). "For instance, B3GNT5 is elevated in acute myelocytic leukemia, ovarian cancer and glioblastoma compared to healthy controls." (PMID 34283051, 2021). "Study has indicated a noteworthy decrease in B3GNT5 expression during differentiation of glioblastoma stem cells, suggesting that B3GNT5 could potentially serve as a connecting link." (PMID 39671359, 2024). "Therefore, in this study, we investigated the association between the expression of B3GNT5 and the malignancy of GBM using the Repository for Molecular Brain Neoplasia Data (REMBRANDT), Gene Expression Omnibus (GEO) (GSE4536), and Ivy Glioblastoma Atlas Project." (PMID 32677340, 2020). "In addition to the role of SSEA-1 as a tumor-initiating marker in glioblastoma multiforme cells, another recent study showed that B3GNT5 was correlated with glioma stem cells, and its expression was significantly downregulated during glioma stem cells differentiation." (PMID 35526049, 2022). "In order to understand the histopathological significance of B3GNT5 expression, we investigated B3GNT5 expression in GBM in terms of regional differences using the Ivy Glioblastoma Atlas Project dataset." (PMID 32677340, 2020).
breast carcinoma (6 papers, 2018 to 2025). "Strikingly, high expression of B3GNT5 was associated with basal subtype of breast cancer cell lines." (PMID 35526049, 2022). "Clinically, elevated expression of B3GNT5 was correlated with high grade, large tumor size and poor survival, indicating poor prognosis of breast cancer patients." (PMID 35526049, 2022). "B3GNT5 enhances SSEA-1 expression and CSCs properties of breast cancer cells through B3GNT5 overexpression and its glycosylation-mediated protein stabilization, promoting tumorigenesis." (PMID 35526049, 2022). "Increased expression of B3GNT5 strongly correlated with the progression of breast cancer, lung cancer, and ovarian cancer." (PMID 35327982, 2022). "To determine the effect of CNVs on B3GNT5 expression, we analyzed the copy number alterations of breast cancer in TCGA, METABRIC and CCLE datasets." (PMID 35526049, 2022). "Since B3GNT5 expression was tightly associated with breast cancer, it was critical to assess whether B3GNT5 is appropriate for breast cancer patients’ diagnosis." (PMID 35526049, 2022). "Finally, we sought to elucidate the association between B3GNT5 expression and patient survival in GSE20685 dataset and an aggregate breast cancer dataset by Kaplan-Meier survival analysis." (PMID 35526049, 2022). "These clinical data support the critical role of B3GNT5 in breast cancer aggressiveness." (PMID 35526049, 2022). "Given the importance of B3GNT5 and SSEA-1 in cancer cell stemness, B3GNT5 might be required for the maintenance of breast cancer cell stemness." (PMID 35526049, 2022). "In addition, we confirmed these findings by qRT-PCR in different subtypes of breast cancer cell lines and clinical samples, showing that B3GNT5 mRNA expression was significantly higher in basal subtype of breast cancer cell lines and triple-negative breast cancer samples that are mostly also BLBC." (PMID 35526049, 2022). "In breast cancer, particularly basal-like breast cancer (BLBC), aberrant glycosylation of B3GNT5 enhances cancer stem cell properties, increasing invasiveness and resistance to therapy." (PMID 40868286, 2025). "Our data demonstrated that low methylation level in promoter regions of B3GNT5 in breast cancer, especially in BLBC, had a positive correlation with high expression of B3GNT5 through analyzing B3GNT5 methylation datasets and gene expression microarray." (PMID 35526049, 2022). "Our data showed that B3GNT5, as the key enzyme responsible for (neo-) lacto-series GSLs synthesis, elevated surface expression of SSEA-1 in breast cancer cells." (PMID 35526049, 2022). "To further characterize the correlation between B3GNT5 expression and basal subtype, we analyzed B3GNT5 mRNA expression in other five gene expression datasets, CCLE, E-TAMB-181, GSE10890, GSE16732, GSE12777, containing 48, 56, 52, 41 and 51 breast cancer cell lines, respectively." (PMID 35526049, 2022). "With the exception of UQCRH and LRP8, the expression levels of genes positively correlated with YBX1, such as CTPS1, FMNL2, CDC20, B3GNT5, MTHFD1L, and CDCA8, were significantly and positively correlated with the expression level of YBX1 in 13 breast cancer cell lines." (PMID 30647855, 2018).
glioma (4 papers, 2020 to 2023). A benign or malignant brain and spinal cord tumor that arises from glial cells (astrocytes, oligodendrocytes, ependymal cells). "We compared the levels of B3GNT5 mRNA expression in normal human astrocytes (NHAs), glioma cell lines (A172, A1207, U87MG, and LN229), and patient‐derived GSCs (GSC11, 20, 23, and 267)." (PMID 32677340, 2020). "B3GNT5 was highly expressed in human GBM and glioma cell lines in culture, and was associated with poor patient survival." (PMID 32677340, 2020). "In conclusion, we demonstrated that elevated B3GNT5 expression was associated with GBM aggressiveness and maintenance of self‐renewal in glioma stem cells." (PMID 32677340, 2020). "Expression of B3GNT5, the key glycosyltransferase in the biosynthesis of the glycosphingolipid, was significantly elevated in GSCs compared with normal astrocytes, glioma cell lines, and their matched differentiated tumor cells." (PMID 32677340, 2020). "Real‐time PCR analysis showed that B3GNT5 was significantly upregulated in GSCs compared with normal astrocytes and glioma cell lines." (PMID 32677340, 2020). "Due to its important role in the progression of glioma, B3GNT5 may serve as a novel candidate molecule for developing new strategies against glioma." (PMID 32677340, 2020). "The expression of B3GNT5 was the highest in GBM compared with low‐ and high‐grade gliomas." (PMID 32677340, 2020). "Since our study demonstrated the elevated expression of B3GNT5 in GSCs, a comparative structural analysis of B3GNT5‐based glycolipids such as SGGL and Lewis X on GSCs will be performed in our next study to elucidate the structure of the major glycolipid controlling the stemness of glioma stem cells." (PMID 32677340, 2020).
acute myeloid leukemia (3 papers, 2020 to 2024). Acute myeloid leukemia (AML) is a group of neoplasms arising from precursor cells committed to the myeloid cell-line differentiation. "B3GNT5-mediated glycosphingolipids are essential for the differentiation of acute myeloid leukemia (AML) cells." (PMID 39671359, 2024). "In addition, B3GNT5‐mediated glycosphingolipids play a key role in the differentiation of acute myeloid leukemia (AML) cells." (PMID 32677340, 2020).
liver cancer (3 papers, 2022 to 2023). An epithelial or non-epithelial malignant neoplasm that arises from the liver. "Moreover, a long noncoding RNA that increases the expression of B3GNT5 was shown to be positively associated with poor prognosis and metastasis in patients with liver cancer." (PMID 37190166, 2023). "MIR4435‐2HG could sponge miR‐136‐5p while the expression of UDP-GlcNAc:betaGal beta-1,3-N-acetylglucosaminyltransferase 5 (B3GNT5) was upregulated in liver cancer tissues." (PMID 35715800, 2022). "It has been revealed that lncRNA MIR4435-2HG may be a potential biomarker for the treatment and prognosis of liver cancer by upregulating the expression of B3GNT5 and may be a novel therapeutic target in gastric carcinoma by targeting the miR-138-5p/Sox4 axis." (PMID 35812755, 2022).
hydatidiform mole (2 papers, 2020 to 2022). A gestational trophoblastic disorder characterized by marked enlargement of the chorionic villi, hyperplasia of the villous trophoblastic cells and hydropic changes. "Although B3GNT5 is well known to exert a vital function in the progression of cancer and embryo development, the underlying mechanisms of B3GNT5 mediated by miR‐30a remain unclear in hydatidiform moles." (PMID 32575164, 2020). "A previous study established that miR‐30a was involved in hydatidiform moles via targeting B3GNT5; however, the biological mechanisms governing this interaction are presently unclear." (PMID 32575164, 2020). "Subsequently, the study identified B3GNT5 as the target of miR‐30a which regulated B3GNT5 and then affected the molecular mechanism governing the development of hydatidiform moles." (PMID 32575164, 2020). "In addition, we found that miR-30a can affect the occurrence of hydatidiform moles by regulating UDP-GlcNAc:betaGal beta-1,3-N-acetylglucosaminyltransferase 5 (B3GNT5)." (PMID 35246136, 2022). "Finally, to test the protein expression of B3GNT5 in the tissue, we performed Western blotting and revealed that although the protein expression of B3GNT5 was decreased in normal placental tissue, its expression was increased in hydatidiform moles." (PMID 32575164, 2020). "This study demonstrated that miR‐30a was a novel target B3GNT5 that serves an important role in the development of hydatidiform moles, suggesting that miR‐30a may serve as a novel potential biomarker or useful diagnostic and therapeutic tool for hydatidiform moles in clinical settings." (PMID 32575164, 2020).
pancreatic cancer (2 papers, 2019 to 2024). "In addition, mRNA expression of B3GNT5 gene was significantly increased in highly metastatic pancreatic cell lines and human pancreatic tumor tissues." (PMID 31273306, 2019). "Moreover, PCR analysis showed significantly increased expression of B3GNT5 mRNA in highly metastatic FG, T3M-4 and HPAF pancreatic cancer cell lines compared to HPNE (hTERT-immortalized human pancreatic epithelial nestin-expressing) cell line." (PMID 31273306, 2019).
Sepsis (2 papers, 2025). Sepsis is defined as life-threatening organ dysfunction caused by a dysregulated host response to infection. "The key genes distinguishing sepsis from healthy conditions include B3GNT5, FUT11, ST3GAL5, MAN1C1, C1GALT1C1, and GALNT14." (PMID 39981259, 2025). "Validation with an independent dataset confirmed the differential expression patterns of B3GNT5, C1GALT1C1, and GALNT14, reinforcing their potential as robust diagnostic biomarkers for sepsis." (PMID 39981259, 2025). "The expression trends of six Golgi-related genes (B3GNT5, FUT11, ST3GAL5, MAN1C1, C1GALT1C1, and GALNT14) aligned with the patterns observed in the hub genes from the initial sepsis dataset analysis." (PMID 39981259, 2025).
breast invasive carcinoma (1 paper, 2024). "On the other hand, we observed downregulation of B3GNT5 in five tumors which include breast invasive carcinoma (BRCA), prostate adenocarcinoma (PRAD), skin cutaneous melanoma (SKCM), testicular germ cell tumor (TGCT), and thyroid carcinoma (THCA)." (PMID 39671359, 2024).
breast tumors (1 paper, 2022). "To determine whether B3GNT5 expression was affected by DNA methylation in breast tumors, we then analyzed methylation and expression of B3GNT5 from two datasets, TCGA and GSE44837." (PMID 35526049, 2022). "Some breast tumors with B3GNT5 overexpression were observed to have no B3GNT5’s copy number amplification, indicating the involvement of other genetic or epigenetic mediators in the upregulation of B3GNT5 expression." (PMID 35526049, 2022).
neuroblastoma (1 paper, 2025). Neuroblastoma (NB) is the most common solid, extracranial childhood tumor. "Among the glycosyltransferase genes regulated in MYCN-A neuroblastoma, we identified B3GNT5 as a gene with a high hazardous score, significantly upregulated in MYCN-A samples." (PMID 39860532, 2025).
Obesity (1 paper, 2010). Accumulation of substantial excess body fat. "About 26% of the heterozygous males and 40% of the homozygous males developed the obese phenotype (P < 0.05 and P = 0.01, respectively), which indicated that the Lc3 synthase gene B3gnt5 probably was one of factors that controlled for lack of obesity." (PMID 21087515, 2010).
salt and pepper syndrome (1 paper, 2024). "The B3gnt5 gene is associated with human disease, like salt and pepper syndrome, which is a rare autosomal recessive progressive neurological disorder." (PMID 38907247, 2024).
thymoma (1 paper, 2023). A neoplasm arising from the epithelial cells of the thymus. "B3GNT5 can be used as potential biomarkers to predict better prognosis of thymoma patients." (PMID 37781041, 2023). "Expression of B3GNT5 and ST3GAL6 was upregulated in thymoma tissues than adjacent normal thymic tissues (p < 0.05)." (PMID 37781041, 2023).
triple-negative breast carcinoma (1 paper, 2022). An invasive breast carcinoma which is negative for expression of estrogen receptor (ER), progesterone receptor (PR), and human epidermal growth factor receptor 2 (HER2). "Thus, we sought to determine whether B3GNT5 could metabolically regulate SSEA-1 expression, a lacto-series carbohydrate structure which overexpressed in triple-negative breast cancer." (PMID 35526049, 2022).
tumor (11 papers, 2013 to 2025). "Similarly, B3GNT5 was implicated as a protective element in patients with PCPG but as a risk factor across eleven other tumor types according to our DSS analysis." (PMID 39671359, 2024). "Here, we identify the involvement of SPPL3 in the actual killing of tumor cells by γδ T cells, which was mediated by downstream nsGSL synthesis as additional knockout of B3GNT5 reestablishes killing." (PMID 39655358, 2025). "Recently, we highlighted the role of neolacto‐series glycosphingolipids (nsGSLs), produced by the enzyme β1,3‐N‐acetylglucosaminyltransferase 5 (B3GNT5), in tumor immune escape." (PMID 39655358, 2025). "By analyzing RNA-seq data from Genotype-Tissue Expression (GTEx) and TCGA databases, we observed differential expression levels of B3GNT5 across various tumor types accompanied by an unfavorable prognostic correlation." (PMID 39671359, 2024). "Our findings offer novel perspectives on the function of B3GNT5 across various cancers, suggesting a potential mechanism by which B3GNT5 influences the tumor microenvironment (TME), cancer immunotherapy, and cancer stem cell (CSC) stemness." (PMID 39671359, 2024). "We then performed a comparative analysis of the correlated signature score for each tumor across the elevated and reduced expression levels of B3GNT5 to explore the plausible roles of B3GNT5 within the tumor microenvironment (TME)." (PMID 39671359, 2024). "Conversely, B3GNT5 expression is negatively related to stromal, ESTIMATE, and immune scores while positively associated with tumor purity score in ESCA, STAD, and LUSC." (PMID 39671359, 2024). "By using five datasets (GES21653, GES22358, GES1456, NKI295 and MEBTABRIC), in which patients were scored for the tumor grades, we found that B3GNT5 was predominantly expressed in high tumor grade, especially in third grade." (PMID 35526049, 2022). "Markedly, MDA-MB231 and SUM159 cells with B3GNT5 knockout significantly reduced tumor growth in vivo compared with wild-type control cells." (PMID 35526049, 2022). "B3GNT5 is pivotal in the biosynthesis of lactosylceramide sphingolipids and regulates embryonic antigens with lacto-series carbohydrate structures, suggesting its role as a biomarker in various tumours." (PMID 39981259, 2025). "Therefore, our findings revealed that B3GNT5 is pivotal in modulating the cell cycle and tumor immune microenvironment in malignant tumor cells." (PMID 39671359, 2024). "Our analysis using two distinct data sources indicates that B3GNT5 expression is inversely associated with CD8+ T lymphocytes, CD4+ T lymphocytes, and natural killer cells, which could help shed light on the connection between B3GNT5 and diverse tumor types." (PMID 39671359, 2024). "B3GNT5, a critical member of the β-1,3-N-acetylglucosaminyl transferase gene family involved in lactose and glycosphingolipids biosynthesis, has been documented to promote tumor-infiltrating T-cell responses." (PMID 39671359, 2024). "Remarkably, high B3GNT5 expression was correlated with a larger tumor size." (PMID 35526049, 2022). "In tumor tissues, the expression of ST3GAL6 was found to be notably reduced, whereas the expression levels of B3GALT2, ABO FUT3, B3GNT3, and B3GNT5 were observed to be significantly elevated." (PMID 37781041, 2023). "Some glycosylation factors showed genomic alterations (SNVs and CNVs) in 15% of tumor samples (namely GPAA1, PIGZ and B3GNT5) with a predominance of amplifications." (PMID 36009354, 2022).